EIF4G2 (eukaryotic translation initiation factor 4 gamma 2)
Description:
Appears to play a role in the switch from cap-dependent to IRES-mediated translation during mitosis, apoptosis and viral infection. Cleaved by some caspases and viral proteases.
Synonyms: DAP5; NAT1; p97; AAG1
Tractability: PROTAC: UniProt records ubiquitination sites on it; ubiquitination databases record sites on it; its protein half-life has been measured.
Gene: Protein-coding gene on chromosome 11 (10,797,050 to 10,808,940, reverse strand). Ensembl gene ENSG00000110321.
Subcellular location (Human Protein Atlas): Cytosol
Pathways (Reactome):
Disease: Dengue Virus Genome Translation and Replication
Immune System: ISG15 antiviral mechanism
Gene Ontology:
Molecular function: cadherin binding; protein binding; RNA binding; translation factor activity, RNA binding; translation initiation factor activity
Biological process: negative regulation of autophagy; positive regulation of cell growth; regulation of translational initiation; cell death; regulation of cell cycle; translational initiation
Cellular component: adherens junction; cytosol; eukaryotic translation initiation factor 4F complex; membrane
Genetic constraint (gnomAD): Loss-of-function variants: 8 observed, 123.01 expected, observed/expected ratio (o/e) 0.065, 90% interval 0.037 to 0.12. The upper end of that interval is the gene's LOEUF score, 0.12, which puts it in group 1 of 6, group 1 being the genes least tolerant of losing a copy. Missense variants: 813 observed, 1,139.7 expected, observed/expected ratio (o/e) 0.71, 90% interval 0.67 to 0.76. Synonymous variants: 414 observed, 386.16 expected, observed/expected ratio (o/e) 1.07, 90% interval 0.99 to 1.16.
Homologues: Orthologues: pig EIF4G2 (99% identical), guinea pig EIF4G2 (99% identical), macaque EIF4G2 (99% identical), rabbit EIF4G2 (99% identical), rat Eif4g2 (99% identical), mouse Eif4g2 (99% identical), chimpanzee EIF4G2 (97% identical), dog EIF4G2 (97% identical), tropical clawed frog eif4g2 (86% identical), zebrafish eif4g2b (83% identical), zebrafish eif4g2a (82% identical), Drosophila melanogaster NAT1 (41% identical). Paralogues in human: EIF4G3 (29% identical), EIF4G1 (29% identical).
Diseases named in the same sentence as EIF4G2 in open-access papers:
EIF4G2 is named in the same sentence as 38 diseases in open-access papers, as found by Europe PMC text mining. Sharing a sentence is not in itself a finding about the gene and the disease. The quoted sentences say what the papers report.
ovarian carcinoma (10 papers, 2016 to 2026). A malignant neoplasm originating from the surface ovarian epithelium. "The functional analysis indicated that the SDHAP1/miR-4465/EIF4G2 regulatory axis was linked to the apoptosis induced by paclitaxel in ovarian cancer." (PMID 41362671, 2026). "We predicted that there may exist an association between lncRNA SNHG7 and EIF4G2, which could participate in the paclitaxel-resistance of ovarian cancer cell." (PMID 34709112, 2021). "Additionally, in ovarian cancer cells, EIF4G2 is implicated in paclitaxel resistance." (PMID 34709112, 2021). "Silence of EIF4G2 is available to stimulate ovarian cancer (OC) patients to regain chemosensitivity to paclitaxel, and strengthen the sensitivity of cisplatin chemotherapy in NSCLC." (PMID 35196197, 2022). "First, we first detected the expression of EIF4G2 through RT-qPCR and Western blotting among four ovarian cancer cell lines (SKOV3, SKOV3-PTX, heyA8, and heyA8-PTX)." (PMID 34709112, 2021). "The interaction of lncRNA SNHG7 and EIF4G2 plays an important role in the migrative and invasive activity and Paclitaxel resistance of ovarian cancer cells." (PMID 34709112, 2021). "The work reveals that lncRNA SNHG7/EIF4G2 is involved in drug resistance of ovarian cancer cells for PTX in vitro." (PMID 34709112, 2021). "To sum up, we firstly discovered the novel mechanism of lncRNA SNHG7/EIF4G2 to affect the PTX-sensitivity in chemo-resistant ovarian cancer cells, which offers a novel insight to further investigate the molecular mechanism of PTX-resistance in ovarian cancer." (PMID 34709112, 2021). "The regulatory network involving the interactions between SDHAP1, miR-4465, and EIF4G2 could represent a promising therapeutic target for treating ovarian cancer that has developed resistance to paclitaxel chemotherapy." (PMID 41362671, 2026). "A recent study showed that lncRNA SDHAP1 upregulated the expression of EIF4G2 by reducing miR-4465 levels in ovarian cancer cells, which suggests that the pseudogenes may regulate gene expression through microRNAs." (PMID 37165454, 2023). "LncRNA SNHG7/ EIF4G2 affects the sensitivity of ovarian cancer cells with PTX -resistance to PTX." (PMID 34709112, 2021). "The regulatory networks involving SDHAP1, miR-4465 and EIF4G2 participate may be potential therapeutic targets for PTX-resistant ovarian cancer." (PMID 34796116, 2021). "Taken together, these results demonstrated that lncRNA SNHG7 could affect the degradation of EIF4G2 to regulate the sensitivity of ovarian cancer to Paclitaxel, inhibit cell viability, migration, and invasion." (PMID 34709112, 2021). "To determine whether the function of lncRNA SNHG7 was relevant to expression of EIF4G2 in paclitaxel-resistant ovarian cancer, we first induced EIF4G2 overexpression through transfecting EIF4G2 overexpression plasmids into SKOV3-PTX or HEYA8-PTX cells." (PMID 34709112, 2021). "We next investigated whether EIF4G2 involve cancer metastasis in paclitaxel-resistant ovarian cancer cells." (PMID 34709112, 2021). "Downregulation of EIF4G2 could induce reacquisition of chemosensitivity to paclitaxel in ovarian cancer and enhance cisplatin chemosensitivity in nonsmall cell lung cancer." (PMID 33526055, 2021). "EIF4G2 has been investigated to be associated with the resistance of ovarian cancer to paclitaxel, which was recognized as a potential target for the therapy of PTX-resistant ovarian cancer." (PMID 34709112, 2021). "Mechanistically, SDHAP1 was shown to increase the expression of the protein eukaryotic translation initiation factor 4 gamma 2 (EIF4G2) by acting as a decoy for miR-4465, which in turn promoted paclitaxel-induced cell death in ovarian cancer cells." (PMID 41362671, 2026). "The anticancer effect of SDHAP1 was accordant with that SDHAP1 upregulated EIF4G2 level by sponging miR-4465 and therefore promoted the PTX-induced apoptosis in ovarian cancer." (PMID 36438489, 2022).
ovarian carcinoma (continued). "Paclitaxel-resistant ovarian cancer cells not only enhanced invasion and migration but also increased the expression of MMP2 and 9 in inducing the overexpression of EIF4G2 when compared to SiRNA- SNHG7 group." (PMID 34709112, 2021). "In mechanism, SDHAP1 upregulates EIF4G2 expression through sponge miR-4465, thereby promoting PTX induced apoptosis in ovarian cancer cells." (PMID 34796116, 2021). "The study firstly revealed the novel mechanism of lncRNA SNHG7/EIF4G2 to affect the PTX-sensitivity in chemoresistant ovarian cancer cells, which offers a novel insight to further investigate the molecular mechanism of PTX-resistance in ovarian cancer." (PMID 34709112, 2021).
osteosarcoma (6 papers, 2020 to 2023). A usually aggressive malignant bone-forming mesenchymal neoplasm, predominantly affecting adolescents and young adults. "eIF4G2 is involved in drug resistance especially in non-small cell lung carcinoma cells as well as metastasis and invasion in osteosarcoma cells." (PMID 32872485, 2020). "EIF4G2 was also found to act as a target of several miRNAs, including miR-379 in osteosarcoma, miR-139-5p in myeloid leukemia, and miR-520c-3p in diffuse large B-cell lymphoma." (PMID 32880393, 2020).
glioblastoma (5 papers, 2020 to 2022). The most malignant astrocytic tumor (WHO grade IV). "A recent study found that LINC01579 promotes cell proliferation by competitively binding with miR-139-5p to upregulate EIF4G2 in glioblastoma." (PMID 36157241, 2022). "LINC01579 was found to promote glioblastoma cell proliferation in a ceRNA manner of absorbing miR-139-5p to increase EIF4G2 expression." (PMID 34722522, 2021). "EIF4G2 was previously identified as a direct target of miR-139 in AML, with luciferase assays identifying binding sites in both the 3′UTR and 5′UTR, while in glioblastoma, only the 3′UTR binding site was validated with reporter assays and also anti-Ago2-mediated RNA-immunoprecipitation assays." (PMID 33562636, 2021). "The role of EIF4G2 in CRC is not well studied, although it is reported to control the G1 phase inhibitor p27Kip1 to alter proliferation in glioblastoma, human embryonic kidney and AML cells." (PMID 33562636, 2021).
breast carcinoma (4 papers, 2017 to 2024). "It is thus likely that in breast cancer, EIF4G2 promotes metastasis through its ability to enhance migration, invasion, and cell survival." (PMID 38129098, 2024). "In metastatic breast cancer cells, knock-down (KD) of EIF4G2 resulted in decreased cell migration in cellular invasion and wound healing assays, and increased apoptosis upon loss of cell adherence." (PMID 38129098, 2024). "In breast cancer too, EIF4G2 depletion affected metastasis but not growth of primary tumors upon injection of EIF4G2KD cells into mice." (PMID 38388710, 2024).
gastric cancer (3 papers, 2022 to 2024). A primary or metastatic malignant neoplasm involving the stomach. "However, the effect of EIF4G2 in gastric cancer (GC) has not been fully explored." (PMID 36157241, 2022).
hepatocellular carcinoma (3 papers, 2021 to 2023). A malignant tumor that arises from hepatocytes. "For example, miR-144-3p interferes with the progression of hepatocellular carcinoma by regulating EIF4G2." (PMID 37340458, 2023).
myeloid leukemia (3 papers, 2020 to 2022). A clonal proliferation of myeloid cells and their precursors in the bone marrow, peripheral blood, and spleen. "For instance, miR-139-5p suppresses aberrant protein translation by downregulating EIF4G2 expression in myeloid leukemia." (PMID 36157241, 2022).
diffuse large B-cell lymphoma (2 papers, 2020 to 2022). "For instance, repression of EIF4G2 is available to distinctively suppress the advancement of acute myeloid leukemia (AML), diffuse large B-cell lymphoma (DLBCL) and human osteosarcoma (HOS)." (PMID 35196197, 2022).
glioma (2 papers, 2019 to 2020). A benign or malignant brain and spinal cord tumor that arises from glial cells (astrocytes, oligodendrocytes, ependymal cells). "These analyses reveal indeed that the expression of EIF4G1 and EIF4G2 is significantly increased in gliomas whereas EIF4G3 is decreased in gliomas and all GBM subtypes." (PMID 31795417, 2019). "Interestingly, after searching the literature and GEPIA databases, it was found that eIF4G2 and YTHDF3 were upregulated in glioma compared with normal brain tissues (GEPIA2 screening condition: log2foldchange cutoff=1, p-value cutoff=0.01)." (PMID 33323543, 2020).
non-small cell lung carcinoma (2 papers, 2020 to 2023). A group of at least three distinct histological types of lung cancer, including non-small cell squamous cell carcinoma, adenocarcinoma, and large cell carcinoma. "Also, eukaryotic translation initiation factor 4 gamma 2 (EIF4G2)–GAB1 fusion has been found in patients with non-small cell lung cancer treated with EGFR TKI." (PMID 37627207, 2023).
osteoarthritis (2 papers, 2020 to 2021). A noninflammatory degenerative joint disease occurring chiefly in older persons, characterized by degeneration of the articular cartilage, hypertrophy of bone at the margins and changes in the synovial membrane. "EIF4G2 expression is promoted in osteoarthritis cartilage tissues, and EIF4G2 may be implicated in the pathogenesis of osteoarthritis." (PMID 34513803, 2021).
viral infection (2 papers, 2023 to 2024). "EIF4G2, as reported in the STRING database appears to play a role in the switch from cap-dependent to IRES-mediated translation during mitosis, apoptosis and viral infection." (PMID 37482618, 2023).
bipolar disorder (1 paper, 2023). A disorder of the brain that causes unusual shifts in mood, energy, activity levels and the ability to carry out day-to-day tasks. "Of particular interest, EIF4G2 were consistently downregulated in both schizophrenia (p = 1.88 × 10−5) and bipolar disorder (p = 0.001)." (PMID 36253440, 2023).
colorectal cancer (1 paper, 2019). A primary or metastatic malignant neoplasm that affects the colon or rectum. "In addition, colorectal cancer cell proliferation and glycolytic metabolism were compared after knockdown LDHA and EIF4G2." (PMID 31375671, 2019).
cyst (1 paper, 2015). A sac-like closed membranous structure that may be empty or contain fluid or amorphous material. "We show that eIF4G and eIF4G2 act redundantly in the germ cells during early gametogenesis to control testes development while knockdown of eIF4G in cyst cells affects meiotic stages and differentiation events." (PMID 25849588, 2015).
endometrial carcinoma (1 paper, 2024). A malignant tumor arising from the epithelium that lines the cavity of the uterine body. "Notably, endometrial cancer (EC) was prominent among the cancers showing reduced EIF4G2 expression and the presence of somatic mutations, representing 14% of all occurrences of the mutations among all examined cancer types." (PMID 38388710, 2024). "Here we assessed its role in endometrial cancer (EC), in a cohort of 280 EC patients across different types, grades, and stages, and found that low EIF4G2 expression highly correlated with poor overall- and recurrence-free survival in Grade 2 EC patients, monitored over a period of up to 12 years." (PMID 38388710, 2024). "In conclusion, our findings strongly support the integration of EIF4G2, KIF5B and KLC1 markers into clinical practice for the management of endometrial carcinoma." (PMID 38388710, 2024). "Here we examined the contribution of the non-canonical translation factor EIF4G2 to endometrial cancer in human patients and cell lines." (PMID 38388710, 2024).
Huntington disease (1 paper, 2016). Huntington disease (HD) is a rare neurodegenerative disorder of the central nervous system characterized by unwanted choreatic movements, behavioral and psychiatric disturbances and dementia. "These polymorphisms were in eIF4G2, a paralog of the nutrient-sensing factor eIF4G; the ceramide synthase gene schlank; and the Drosophila homolog of huntingtin, the gene underlying human Huntington’s disease." (PMID 27809764, 2016).
leukemia (1 paper, 2022). A malignant (clonal) hematologic disorder, involving hematopoietic stem cells and characterized by the presence of primitive or atypical myeloid or lymphoid cells in the bone marrow and the blood. "We recently confirmed Eif4g2 as a critical target of miR-139 in mouse MLL-AF9 AML, suggesting that Eif4g2 is a more common miR-139 target in leukemia." (PMID 35269391, 2022).
lung diseases (1 paper, 2022). "For the majority of genes such as Elac2, Csnk1a1, Eif3a, Eif4g2, Tmed2 and Mpv17l, a role in the pathogenesis of lung diseases was indicated by previous studies, although their functions in the neonatal lung remain unexplored." (PMID 36271035, 2022).
male infertility (1 paper, 2015). The inability of the male to effect fertilization of an ovum after a specified period of unprotected intercourse. "We observed differential expression of a number of transcripts, such as PRM1, SPATA18, TNP1, EIF4G2, CANX, RANBP9, TCP11, which have previously been associated with male infertility." (PMID 25973848, 2015).
metastatic tumors (1 paper, 2024). "Moreover, EIF4G2 protein levels were elevated in metastatic tumors compared to non-metastatic tumors from a very small cohort of triple negative breast cancer patients, and high mRNA levels correlated with poor metastasis-free survival rates." (PMID 38388710, 2024).
myocardial infarction (1 paper, 2023). Gross necrosis of the myocardium, as a result of interruption of the blood supply to the area, as in coronary thrombosis. "The upregulation of miR-24-3p by silencing the long non-coding RNA MCM3AP antisense RNA 1 reduces EIF4G2 and speeds up the proliferation and migration of vascular endothelial cells in rats with myocardial infarction." (PMID 38275601, 2023).
pancreatic cancer (1 paper, 2022). "It was found that MYEOV, GPRC5A, SERPINB5, KRAS, EGFR, and EIF4G2 were all significantly elevated in pancreatic cancer tissues, and the expression trends of GPRC5A, SERPINB5, KRAS, EGFR, and EIF4G2 in different stages were nearly identical." (PMID 36358856, 2022). "We also validated the role of ceRNA network genes such as GPRC5A, SERPINB5, KRAS, EGFR, EIF4G2, and PDCD4 in pancreatic cancer." (PMID 36358856, 2022). "We analyzed mRNA expression levels of MYEOV, GPRC5A, KRAS, EGFR, SERPINB5, EIF4G2, and PDCD4 in pancreatic cancer tissues and normal tissues adjacent to pancreatic cancer from three pancreatic cancer patients." (PMID 36358856, 2022). "It was noted that MYEOV could serve as a ceRNA by producing molecular sponging effects on hsa-miR-103a-3p and hsa-miR-107, thus affecting the role of GPRC5A, SERPINB5, EGFR, KRAS, EIF4G2, and PDCD4 on pancreatic cancer progression." (PMID 36358856, 2022). "To investigate whether MYEOV acts as ceRNA to exert certain regulatory effects on genes such as GPRC5A, SERPINB5, KRAS, EGFR, EIF4G2, and PDCD4, we analyzed the differential expression of these genes in pancreatic cancer and normal pancreatic tissues by the GEPIA database." (PMID 36358856, 2022). "The increase in EIF4G2-related central memory cells, iTreg cells, and Tr1 cells, with little change in most immune cells, may also account for its lack of significant impact in the pancreatic cancer survival analysis." (PMID 36358856, 2022).